SOS2 (SOS Ras/Rho guanine nucleotide exchange factor 2)
Description:
Acts as guanine nucleotide exchange factor (GEF) for RAS proteins. Catalyzes the GDP-to-GTP exchange, resulting in an increase of the active GTP-bound form of HRAS. Acts as a key modulator of PI3K-AKT signaling.
Synonyms: SOS-2; NS9
Tractability: Small molecule: a structure with a bound ligand is known. Antibody: its Gene Ontology location is reachable by antibodies, with medium confidence. PROTAC: ubiquitination databases record sites on it; its protein half-life has been measured.
Gene: Protein-coding gene on chromosome 14 (50,117,130 to 50,231,906, reverse strand). Ensembl gene ENSG00000100485.
Subcellular location (Human Protein Atlas): Nucleoplasm; Vesicles
Pathways (Reactome):
Signal Transduction: G alpha (12/13) signalling events; NRAGE signals death through JNK; RAC1 GTPase cycle
Developmental Biology: Activation of RAC1
Immune System: Interleukin-15 signaling
Gene Ontology:
Molecular function: protein binding; guanyl-nucleotide exchange factor activity; protein heterodimerization activity
Biological process: Ras protein signal transduction; insulin receptor signaling pathway; small GTPase-mediated signal transduction
Cellular component: cytosol; plasma membrane
Genetic constraint (gnomAD): Loss-of-function variants: 17 observed, 61.41 expected, observed/expected ratio (o/e) 0.28, 90% interval 0.19 to 0.41. The upper end of that interval is the gene's LOEUF score, 0.41, which puts it in group 1 of 6, group 1 being the genes least tolerant of losing a copy. Missense variants: 755 observed, 891.24 expected, observed/expected ratio (o/e) 0.85, 90% interval 0.8 to 0.9. Synonymous variants: 288 observed, 303.58 expected, observed/expected ratio (o/e) 0.95, 90% interval 0.86 to 1.05.
Gene-disease validity (ClinGen):
ClinGen rates the evidence that SOS2 causes each of these diseases.
Noonan syndrome (autosomal dominant): Definitive. Noonan Syndrome (NS) is characterized by short stature, typical facial dysmorphism and congenital heart defects.
Homologues: Orthologues: chimpanzee SOS2 (99% identical), macaque SOS2 (99% identical), pig SOS2 (97% identical), dog SOS2 (97% identical), guinea pig SOS2 (96% identical), rabbit SOS2 (96% identical), mouse Sos2 (95% identical), rat Sos2 (93% identical), tropical clawed frog sos2 (84% identical), zebrafish sos2 (73% identical). Paralogues in human: SOS1 (70% identical), RAPGEF2 (19% identical), RAPGEF6 (17% identical), RASGRF1 (15% identical), RASGRF2 (14% identical), RAPGEF1 (12% identical), RASGRP1 (10% identical), RALGDS (10% identical), RAPGEF4 (10% identical), RASGRP3 (9% identical), RAPGEF3 (9% identical), RASGRP4 (9% identical), and 12 more.